CTLA4 (cytotoxic T-lymphocyte associated protein 4)
Diseases named in the same sentence as CTLA4 in open-access papers (continued):
Sharing a sentence is not in itself a finding about the gene and the disease.
melanoma (continued). "However, some data shows that this group of HLA proteins may be predominantly responsible for the sensitivity of melanoma cells to anti-CTLA-4 treatment, while the expression of HLA class II molecules predicts response to anti-PD-1 therapy." (PMID 32517213, 2020). "In addition, albeit less potently than SK1 silencing, pharmacological inhibition of SK1 by SKI-I9 significantly improved the anti-CTLA-4 therapy on established Yumm melanoma, and led to a potent increase of tumor rejection and animal survival, as well as CD8/Treg ratio." (PMID 31974367, 2020). "Furthermore, we discuss that stratification based on melanoma subtype might improve response rates to immune checkpoint blockade therapy (anti-PD-1/anti-PD-L1/anti-CTLA-4) and adoptive cell therapy." (PMID 33256089, 2020). "Patients with advanced melanoma could have received prior anti-CTLA4 therapy (7/28 patients)." (PMID 32858956, 2020). "Previous studies have found that anti-CTLA-4 antibody depletes tumor-infiltrating Tregs in the melanoma mouse model, which expressed granulocyte macrophage colony-stimulating factor and Fcγ receptor on macrophages was involved with depletion of Tregs by an anti-CTLA-4 antibody." (PMID 35582437, 2020). "Whether such a mechanism occurs within DC in the TME is currently unknown, but the authors of this study did find that silencing CTLA‐4 in bone marrow‐derived DC (BMDC) prior to electroporation with B16 melanoma mRNA improved the antitumor efficacy of BMDC vaccination against established tumors." (PMID 32508018, 2020). "Since the approval of the first immune checkpoint (CTLA-4) inhibitor ipilimumab in 2011 and programmed death-1 (PD-1) blocking monoclonal antibodies pembrolizumab and nivolumab thereafter, an increasing proportion of patients with unresectable advanced melanoma achieved long-term overall survival." (PMID 31182961, 2019). "Therefore, as PD-1 and CTLA4 have different mechanisms of action to regulate T-cell activation, combined treatment with PD-1- and CTLA4-inhibitors has demonstrated enhanced effectiveness in several clinical trials for advanced-stage melanoma." (PMID 31795835, 2019). "However, expression of CTLA-4, PD-L1, and PD-1 was increased in H-1PV-infected melanoma cells." (PMID 31192129, 2019). "However, in melanoma, recent deep molecular profiling of a cohort of longitudinal tissue samples from metastatic melanoma patients treated with sequential CTLA-4 blockade followed by PD-1 blockade demonstrated that a more clonal T cell repertoire was predictive of response to PD-1 blockade." (PMID 30249211, 2018). "As a-CTLA4-TGFβRII effectively counteracted tumor-infiltrating Tregs in vivo, we examined its ability to increase tumor-reactive IFNγ expression in T cells and inhibit tumor growth in human melanoma tumor-bearing NSG mice that were immune reconstituted with matched HLA A2+ human BM CD34+ cells." (PMID 29467463, 2018). "In clinical trials, both anti-cytotoxic T lymphocyte-associated protein 4 (CTLA-4; e.g., ipilimumab) and anti-programed cell death-1 (PD-1) agents (e.g., nivolumab, pembrolizumab) have demonstrated improved overall survival, PFS and ORR in patients with advanced melanoma compared with chemotherapy." (PMID 30190927, 2018). "However, consistent with previous clinical studies and its highly immunogenic profile, both anti-CTLA-4 and anti-PD-1 antibodies were highly effective in suppressing the growth of the melanoma cell xenografts, including a significant dose-dependent response with anti-CTLA-4 therapy." (PMID 30185216, 2018). "Moreover, fecal microbial transplantation from humans to germ-free mice favored the outgrowth of B. fragilis with anticancer properties in melanoma-bearing mice treated with CTLA-4 antibodies, demonstrating that these bacteria can synergize with checkpoint blockade therapy." (PMID 29735917, 2018).
melanoma (continued). "Some years later, it was reported that the baseline serum levels of soluble NKG2DLs (ULBP-1 or -2) could discriminate melanoma patients treated with anti-CTLA-4 mAb plus chemotherapy with improved (median 33.6 months) or poor (median 9.8 or 6.6 months, respectively) OS." (PMID 30004433, 2018). "Similarly, agents such as ipilimumab, that inhibit CTLA-4 for melanoma treatment, and nivolumab that inhibits PD-1 used for treating non-small cell lung cancer, melanoma and renal carcinoma have limited success (20–30% response rate) although drug-induced autoimmune diseases is a major concern." (PMID 29541939, 2018). "Ipilimumab (an anti- CTLA-4 immunotherapy for advanced melanoma) and fotemustine (a chemotherapy for melanoma with cerebral metastases) are the only two drugs that could be individualised, as these are the only two treatments of advanced melanoma documented in the FICHCOMP database." (PMID 28789648, 2017). "Cytotoxic T lymphocyte antigen-4 (also termed cytotoxic T-lymphocyte-associated protein 4), is a crucial regulator of T cell activation and ipilimumab, a human IgG1 mAb targeted to this molecule was the first ICB drug to show clinical efficacy in advanced melanoma and a number of other cancer types." (PMID 29276510, 2017). "In these studies, feces from only one cluster of melanoma patients promoted colonization of immunogenic B. thetaiotaomicron and B. fragilis in mice, and these animals were the only fecal transplant recipients to mount effective antitumor responses following α-CTLA-4 Ab treatment." (PMID 29209327, 2017). "This could at least explain the modest cytotoxicity exerted by pre-existing T-cells observed during ipilimumab therapy as well as the relationship between neo-antigens and improvement of progression free survival (PFS) in melanoma patients treated with the anti-CTLA4 MoAb." (PMID 29285320, 2017). "In a Phase III randomized clinical trial the anti-CTLA-4 mAb ipilimumab increased the 5-years rates of recurrence-free survival (40.8% versus 30.3%), OS (65.4% versus 54.4%) and distant metastasis–free survival (48.3% versus 38.9%) as compared to placebo in high-risk stage III melanoma patients." (PMID 29290886, 2017). "Since pentoxifylline substantially reduces the β-catenin activity in melanoma cells, this drug might be useful in induction of the melanoma response to CTLA-4, PD-L1 and PD-1 blockade in a subset of patients with the WNT/ β-catenin pathway-driven exclusion of the host immune response." (PMID 27351373, 2016). "Moreover, high levels of serum VEGF in patients with advanced melanoma was associated with poorer overall survival when treated with ipilimumab (anti-CTLA4 antibody) and also predicted lack of response to high-dose IL-2 therapy." (PMID 27330805, 2016). "Given the high mutational load and increased immunogenicity of human melanoma with the same genotype, our findings encourage testing α-CD137 and α-PD-1 alone or in combination with SBRT clinically, particularly in patients refractory to α-CTLA-4 and/or α-PD-1 therapy." (PMID 27160390, 2016). "Therefore, in this study, we aimed to identify which T cell modulating antibody combinations (α-CTLA-4, α-PD-1, α-CD137) could enhance the anti-tumor effect of SBRT in an inducible mouse model of human BRAFV600-mutant and PTEN-deficient melanoma." (PMID 27160390, 2016). "Furthermore, application of the PTML to two independent, previously reported cohorts of advanced melanoma patients treated with anti-CTLA-4 and for which WES data was available (n = 110 and n = 64) also demonstrated a strong association between the PTML and clinical benefit." (PMID 27776519, 2016). "This may indicate that some types of immunotherapy, such as CTLA-4 and PD-1/PD-L1 blockade as monotherapy, may not be as effective as other cancers with higher mutational loads (e.g., melanoma and non-small cell lung cancer) that tend to respond better." (PMID 26359351, 2015).
melanoma (continued). "Thus, blocking antibodies against CTLA4 such as ipilimumab, already approved for clinical use in melanoma patients to down regulate tumor-induced tolerance and immune suppression, might find a clinical application in colonic carcinogenesis." (PMID 25595911, 2015). "Three monoclonal antibodies directed to two different immune checkpoint molecules - CTLA-4 (cytotoxic T-lymphocyte antigen 4) and PD-1 (programmed death receptor 1) − have now been approved by the U.S. Food and Drug Administration for treatment of melanoma and NSCLC patients." (PMID 26439694, 2015). "Similarly, the improved survival after treatment of melanoma patients with CTLA-4 blocking antibodies may also involve Cbl-b down-regulation as activation of CTLA-4 increases Cbl-b levels by transcriptional regulation." (PMID 25815272, 2015). "A clinical study combining agents targeting cytotoxic-T-lymphocyte-associated antigen 4 (CTLA-4), which is thought to influence Treg function, and PD-1, which blocks signals that inhibit T cell function, has reported impressive responses in patients with advanced melanoma." (PMID 26406376, 2015). "Ongoing efforts to identify biomarkers to predict the response to anti-CTLA-4 therapy are under way just as additional studies to identify those patients most likely to benefit from MMP-23 inhibition are needed in parallel to those of the role of MMP-23 in melanoma." (PMID 25491880, 2014). "Furthermore, we found, by the TMA approach, that about 2/3 of melanoma tissues expressed CTLA-4." (PMID 23634660, 2013). "Indeed, the notion that melanoma cells can express CTLA-4 is more recent." (PMID 23634660, 2013). "Our data are not in contrast with the commonly accepted notion that Ipilimumab can block the action of CTLA-4 at the cell surface of T cells; this leads to a stronger immune anti-tumor response that according to previous report is the reason why Ipilimumab is working in patients with melanoma." (PMID 23634660, 2013). "The triggering of ADCC detected using Ipilimumab with ex-vivo NK cells and CTLA-4+ melanoma targets was conceivably due to the binding of Ipilimumab to FcγRIIIA expressed on NK cells as the addition of an anti-FcγRIIIA antibody to the assay could almost block the ADCC (P < 0.0001)." (PMID 23634660, 2013). "Host adaptiveimmune responses have been described in melanoma with a main focus on melanomaspecific T cell responses, and supported by successful case scenarios usingimmunotherapeutic strategies such as dendritic cell vaccines, adoptive T celltherapies, and CTLA4 monoclonal antibodies." (PMID 21559411, 2011). "Additionally, in a phase I study of 19 patients receiving anti-CTLA-4 monoclonal antibody with multiple melanoma peptides and Montanide ISA 51, three of four (75%) patients with the CTLA-4 allele JO 30 (GG) developed autoimmune symptoms, and only two (50%) experienced disease relapse." (PMID 21044351, 2010). "Intriguingly, a CTLA-4 polymorphism conferring low-level expression was found to be associated with higher frequencies of autoimmune toxicity among 19 melanoma patients treated concurrently with MDX-010 (ipilimumab) anti-CTLA-4 monoclonal antibody and a melanoma peptide vaccine." (PMID 21044351, 2010). "Collectively, these data show that in melanoma, although γδ T cells appear capable of producing cytokines, induction of LAG-3 and CTLA-4 in response to TCR and IL-15 is impaired." (PMID 41310392, 2026). "Pepple’s study also detected strong immune-enhancing responses in mouse melanoma and hepatocellular carcinoma models after administration of anti-CTLA-4, followed by mechanical ablation the next day, and two subsequent anti-CTLA-4 treatments." (PMID 40433381, 2025). "The approval of Ipilimumab, an anti-CTLA-4 monoclonal antibody, by the FDA in 2011 for advanced melanoma marked a pivotal milestone in cancer immunotherapy." (PMID 40474230, 2025).
melanoma (continued). "This study aimed to evaluate the expression of the immune checkpoints PD‐1/PD‐L1 and CTLA‐4 by RNAscope in situ hybridization (ISH) in canine OM, to investigate their expression pattern and explore their potential role in melanoma progression." (PMID 39789732, 2025). "Ipilimumab, a therapy targeting cytotoxic T-lymphocyte antigen 4 (CTLA-4), was well tolerated but demonstrated little effectiveness, though it is FDA approved for the treatment of unresectable childhood melanoma." (PMID 39796780, 2025). "A phase I study evaluated the combination of evofosfamide (a hypoxia-activated prodrug) and ipilimumab (a CTLA-4 ICI) in advanced solid malignancies, including immunotherapy-resistant melanoma." (PMID 40867277, 2025). "Among patients with melanoma treated with anti-CTLA-4 therapy, the incidence of VLD in those receiving anti-CTLA-4 therapy ranges from 2% to 9%." (PMID 40861456, 2025). "To evaluate the effects of combination ICI (subsequently referred to as ‘combi-ICI’) on the CNS, we used a clinically relevant cancer survivor model of melanoma: syngeneic mouse model (D4M-UV2 cells) and combination therapy of CTLA-4 and PD-1 blockade in mice." (PMID 40313772, 2025). "PD-1, PD-L1, and CTLA-4 inhibitors have significantly improved OS and prolonged PFS in various malignancies, such as NSCLC, HCC, melanoma, and TNBC." (PMID 40361336, 2025). "Anti PD‐1, anti PD‐L1, and anti CTLA‐4 immunotherapies have shown the most promising outcomes in the treatment of various malignancies including breast cancer, lung cancer, CRC, and melanoma." (PMID 40243372, 2025). "The promotion of high levels of PD-L1 on both melanoma and immune cells by IFN-γ led to the development of resistance to anti-CTLA-4 in combination with radiation." (PMID 40108693, 2025). "The simultaneous inhibition of the ICs PD-L1 and CTLA-4, combined with the administration of the CSC-DC vaccine, improved the anticancer efficacy in a mouse model of melanoma." (PMID 40647402, 2025). "The presence of TLS and active B cell infiltrates in the pre-treatment biopsies of melanoma, RCC, STS, and UC has been demonstrated to correlate with the response to PD-1 inhibition or the combination of PD-1 and CTLA-4." (PMID 40038799, 2025). "Despite significant advances in targeted (BRAFi + MEKi) and immune (anti-PD1/PD-L1, anti-CTLA4, and anti-LAG3) therapies, treatment options for NRASmut melanoma remain limited." (PMID 41035005, 2025). "As a result, CTLA-4 Nb-IL-2 and CTLA-4 Nb-Fc elicited more robust and sustained immune reactions in CD8+ T cells across hepatocellular carcinoma, breast cancer, and melanoma mouse models." (PMID 40474230, 2025). "The emergence of immunotherapy, including PD-1 inhibitors (e.g., nivolumab and pembrolizumab) and anti-CTLA-4 agents (e.g., ipilimumab), has marked a paradigm shift in the management of stage III melanoma." (PMID 40161129, 2025). "It was revealed that the dual blockades of PD-1 and CTLA-4, in contrast to individual inhibition, significantly enhanced the CD8+ T cells/Tregs and CD8+ T cells/MDSCs ratios within the tumor in mice with melanoma." (PMID 40861801, 2025). "Ipilimumab, a monoclonal antibody targeting CTLA-4, was the first immune checkpoint inhibitor (ICI) to receive FDA approval, demonstrating significant clinical benefit in patients with advanced melanoma compared to the gp100 peptide vaccine." (PMID 41303538, 2025). "It was found that anti-CTLA-4 treatment mainly affected CD4+ T cells 32, and induced cytotoxic CD4+ T cells in melanoma patients." (PMID 40861801, 2025). "In melanoma-bearing mice on a Western diet, those receiving triple immune checkpoint blockade (ICB) targeting PD-1, CTLA-4, and LAG-3 showed diminished response compared to lean controls." (PMID 40565936, 2025). "Beyond PD-1/PD-L1 and CTLA-4, other checkpoints like TIM-3, TIGIT, and VISTA are co-expressed in melanoma TME, particularly on Tregs, marking them as potential targets." (PMID 40936894, 2025).
melanoma (continued). "The GSE91061 cohort documented the effects of anti‐PD‐1 and anti‐CTLA4 immunotherapy in patients with melanoma and non‐small cell lung cancer, while GSE93157 studied the responses of melanoma and lung cancer patients to anti‐PD‐1 treatment." (PMID 40576208, 2025). "These immune checkpoint inhibitors (CPIs), particularly ones targeting PD-1, CTLA4 and LAG3, have revolutionized the treatment of many cancers and have been especially effective in the treatment of melanoma." (PMID 41325134, 2025). "Combination CTLA-4 (ipilimumab) and PD-1 (nivolumab) checkpoint inhibition (dual-ICI) improves survival in patients with advanced melanoma." (PMID 40778883, 2025). "In murine models of small-cell lung cancer, melanoma, and TNBC, BET inhibitor enhances tumor antigen presentation, increases cytotoxic T cell infiltration, and synergizes with PD-1/PD-L1 or CTLA-4 checkpoint blockade." (PMID 41583469, 2025). "Two-hundred fifty-two patients with melanoma and NSCLC who received CTLA-4 inhibitor ipilimumab or PD-1 inhibitors nivolumab or pembrolizumab and who underwent staging CT of the chest and abdomen were retrospectively included." (PMID 39294304, 2025). "In 2011, the use of anti-CTLA-4 was first approved drug by the U.S. food and drug administration (FDA) for the treatment of advanced melanoma patients, based on a significant improvement in overall survival." (PMID 40621453, 2025). "Therapeutic inhibition of CTLA-4, which aims to invigorate de novo priming and expansion of tumor-specific T cells was indeed less efficient in mice bearing MLKL−/− melanomas." (PMID 40345706, 2025). "Other authors reported the presence of CTLA-4 and IDO in specific canine cancer types, such as B-cell lymphoma and melanoma, and found that B7-H4 was overexpressed in bladder cancer." (PMID 40788962, 2025). "A turning point was a 2020 Phase III trial that demonstrated the superiority of ipilimumab (an anti-CTLA-4 antibody) over high-dose IFN-α2b, shifting the treatment paradigm for operable melanoma towards ICI immunotherapy." (PMID 41373826, 2025). "While most TCGA datasets were from non-immunotherapy-treated cohorts, two datasets contained immunotherapy-exposed patients: TCGA-SKCM (melanoma; 24 patients) and TCGA-BLCA (urothelial cancer; two patients), both treated with anti-PD-1/CTLA-4." (PMID 40649716, 2025). "ICIs have demonstrated significant efficacy in non-small cell lung cancer (NSCLC), hepatocellular carcinoma (HCC), melanoma, and triple-negative breast cancer (TNBC) by targeting checkpoint proteins such as PD-1, PD-L1, and CTLA-4." (PMID 40361336, 2025). "ICIs targeting CTLA-4, PD-1 and PD-L1 have dramatically improved survival rates across diverse cancer types, including non-small cell lung cancer (NSCLC), melanoma, renal cell carcinoma (RCC), hepatocellular carcinoma, and triple negative breast cancer." (PMID 40561796, 2025). "Ipilimumab which blocks the checkpoint protein CTLA-4, was the first FDA approved ICI in 2011, for the treatment of malignant melanoma." (PMID 40011240, 2025). "Meanwhile, the Kaplan-Meier Plotter database showed that WFDC13, highly expressed in melanoma and BLCA patients, indeed had a poor prognosis when they received anti-PD1, anti-PDL1, or anti-CTLA4 antibodies (Fig. A4A)." (PMID 41502505, 2025). "Targeting CXCR2 has been shown to significantly reduce NET formation in melanoma, and inhibition of NET formation has been observed to enhance tumor sensitivity to double checkpoint blockade using PD-1 and CTLA-4 inhibitors." (PMID 40352926, 2025). "Under the guidance of immunogenomics, how might combination strategies involving CTLA-4/PD-1 inhibitors and small-molecule agents, next-generation immune checkpoint inhibitors, oncolytic viruses, cellular therapies, and vaccines reshape the therapeutic landscape of melanoma brain metastases?" (PMID 40666508, 2025). "In melanoma, VISTA expression rises following PD-1/CTLA-4 blockade, suggesting a compensatory upregulation." (PMID 40821795, 2025).